UBA1 (ubiquitin like modifier activating enzyme 1)
Diseases named in the same sentence as UBA1 in open-access papers (continued):
Sharing a sentence is not in itself a finding about the gene and the disease.
atherosclerosis (3 papers, 2020 to 2023). A disease characterized by the build-up of fatty material and calcium deposition in the arterial wall resulting in partial or complete occlusion of the arterial lumen. "PYR-41 inhibits the ubiquitin-activating enzyme UBA1 to alleviate atherosclerosis and suppress the inflammatory response of macrophage in ApoE-/- mice." (PMID 37244925, 2023). "Next, we examined the role of increased macrophage UBA1 expression in the diet-induced atherosclerosis in Apoe-/- mice, using a specific inhibitor PYR-41." (PMID 32258175, 2020). "In this study, we showed that UBA1 played an important role in the development of atherosclerosis in the Apoe-/- mice." (PMID 32258175, 2020). "Together, our data indicated that UBA1 expression was upregulated and mainly derived from macrophage in diet-induced atherosclerosis in Apoe-/- mice." (PMID 32258175, 2020). "Inhibition of UBA1 decreased diet-induced atherosclerosis by reducing macrophage infiltration and plaque necrosis." (PMID 32258175, 2020). "Our data for the first time identified an inhibitory effect of UBA1 inhibitor PYR-41 in atherosclerosis, therefore might expand the therapeutic potent of UBA1 as a potential pharmaceutical target against atherosclerosis." (PMID 32258175, 2020). "Our data suggested that UBA1 might be explored as a potential pharmaceutical target against atherosclerosis." (PMID 32258175, 2020). "Macrophage UBA1 might be explored as a potential pharmaceutical target against atherosclerosis." (PMID 32258175, 2020). "To further identify the origin of UBA1 expression, we costained UBA1 with CD68, a marker of macrophages, which is the main type and also majority of functional cells in atherosclerosis." (PMID 32258175, 2020). "UBA1 inhibitor PYR-41 can inhibit ox-LDL-induced proinflammatory cytokine expression, NADPH oxidases and lipid deposition in macrophage, thereby suppressing atherosclerosis in ApoE-/- mice with blunted proinflammatory responses in macrophage." (PMID 37244925, 2023). "We then explored the atherosclerosis development in the Apoe-/- mice with or without UBA1 inhibition by PYR-41, after 8 weeks on the atherogenic diet feeding." (PMID 32258175, 2020). "Inactivation of UBA1 by the specific inhibitor PYR-41 did not alter the main metabolic parameters during atherogenic diet feeding but suppressed atherosclerosis development with less macrophage infiltration and plaque necrosis." (PMID 32258175, 2020). "We demonstrated that UBA1 expression was upregulated and mainly derived from macrophages in the atherosclerotic plaques and inactivation of UBA1 by PYR-41 suppressed atherosclerosis development probably through inhibiting macrophage proinflammatory response and oxidative stress." (PMID 32258175, 2020). "However, whether UBA1 is involved in atherosclerosis is not defined." (PMID 32258175, 2020). "However, whether UBA1 contributes to atherosclerosis is not defined." (PMID 32258175, 2020).
essential thrombocythemia (3 papers, 2023 to 2025). A chronic myeloproliferative neoplasm that involves primarily the megakaryocytic lineage. "One patient with long-standing Calreticulin (CALR)-mutated essential thrombocythemia (ET) later acquired a UBA1 mutation; the UBA1-mutant clone progressively overtook the CALR-mutant clone, extinguishing the ET phenotype as VEXAS features emerged." (PMID 40791602, 2025). "Both the CALR clone and the essential thrombocythemia phenotype disappeared at the time of the identification of the UBA1 gene mutation." (PMID 36662445, 2023).
leukocytoclastic vasculitis (3 papers, 2022 to 2025). "UBA1 mutation was found in the biopsies related to neutrophilic dermatitis but in none of the other histological patterns (leukocytoclastic vasculitis and septal panniculitis)." (PMID 35172893, 2022).
rheumatoid arthritis (3 papers, 2023 to 2025). A chronic, systemic autoimmune disorder characterized by inflammation in the synovial membranes and articular surfaces. "Auranofin, an orally administered gold compound long used in rheumatoid arthritis, has emerged as a novel UBA1-reactivating agent." (PMID 40791602, 2025). "In this study, we report that auranofin (AF), a drug currently used to treat rheumatoid arthritis, is a potent enhancer of UBA1 activity." (PMID 37558718, 2023). "Here, the authors found that auranofin, a rheumatoid arthritis drug, can significantly boost UBA1 activity." (PMID 37558718, 2023). "Here we report that auranofin, a drug approved for the treatment of rheumatoid arthritis, is a potent UBA1 activity enhancer." (PMID 37558718, 2023). "In this study, we discovered that AF, a clinical drug used for the treatment of rheumatoid arthritis, potently enhances UBA1 activity." (PMID 37558718, 2023).
X-linked disease (3 papers, 2020 to 2022). X-linked form of disease. "In 2022, VEXAS (vacuoles, E1 enzyme, X-linked, autoinflammatory, somatic) syndrome, an established X-linked disease associated with a somatic mutation in UBA1, is considered as a differential diagnosis for AOSD particularly in elderly." (PMID 36578047, 2022).
Alzheimer disease (2 papers, 2020 to 2025). A progressive, neurodegenerative disease characterized by loss of function and death of nerve cells in several areas of the brain leading to loss of cognitive function such as memory and language. "Alterations in the protein levels and function of UBA1 have been related to multiple neurodegenerative disorders, such as spinal muscular dystrophy and Alzheimer’s disease." (PMID 39773572, 2025).
glioma (2 papers, 2022 to 2024). A benign or malignant brain and spinal cord tumor that arises from glial cells (astrocytes, oligodendrocytes, ependymal cells). "In the order of significance, high gene expression of UBA1, UBA6, and UBA3/NAE2 were associated with significantly shorter survival times in the French glioma dataset (chi = 26.79, p = 2.3 × 10−7, chi = 21.04, p = 4.5 × 10−6, chi = 8.79, p = 3.0 × 10−3, respectively)." (PMID 36293188, 2022). "At the single‐cell level, UBA1 is highly expressed in malignant cells and macrophages in various cancers (BRCA, DLBC, glioma, LIHC, OV and PAAD)." (PMID 39183260, 2024). "UBA1 is expressed by macrophages and malignant cells in BRCA, DLBC, glioma, LIHC, OV and PAAD." (PMID 39183260, 2024).
melanoma (2 papers, 2016 to 2025). A malignant, usually aggressive tumor composed of atypical, neoplastic melanocytes. "Additionally, validation with a melanoma tissue microarray confirmed that protein levels of UBA1 were strongly negatively correlated with the abundance of intratumoral CD8+ T cells." (PMID 39540840, 2025). "Reassuringly, no obvious signs of gross tumor formation were noted over a 6-month period in control mice treated with AAV9-UBA1, consistent with previous work showing that syngeneic transplantation of UBA1-overexpressing melanoma cells did not significantly affect tumor formation in mice." (PMID 27699224, 2016).
motor neuron disease (2 papers, 2019 to 2023). "Given the involvement of UBA1 in this process and its role in motor neuron diseases, understanding the pathways that are most affected under conditions of cellular stress could provide valuable insight into potential therapies." (PMID 31200561, 2019).
myeloid malignancies (2 papers, 2023 to 2025). "We further detected a clear sex bias in the occurrence of UBA1 somatic variants in myeloid malignancies, which is supportive of the potential clonal advantage conferred by UBA1 variants." (PMID 36823397, 2023). "In these male patients of myeloid malignancies, we observed three different scenarios: (i) UBA1 variants as the main clone, (ii) UBA1 variants as subclonal events in combination with known leukemic driver events, and (iii) UBA1 variants as a secondary major driver event following treatment." (PMID 36823397, 2023).
polyarthritis (2 papers, 2021). "Two patients harbored the recently identified mutations in UBA1 (2 and 12), both having H-SS associated with a febrile polyarthritis." (PMID 34671345, 2021).
prostate adenocarcinoma (2 papers, 2024 to 2025). "We found that UBA1 was upregulated in 40% (2/5) of prostate adenocarcinomas and 60% (6/10) of mCRPCs." (PMID 39540840, 2025). "To confirm the upregulation of UBA1 at the protein level, we performed immunoblot analysis on the lysates from normal prostate tissues, primary prostate adenocarcinoma, and mCRPC." (PMID 39540840, 2025). "According to the UALCAN database, the levels of UBA1 methylation in prostate adenocarcinoma (PRAD), TGCT, BLCA, LIHC, KIRC and THCA tissues significantly decreased compared to normal tissues." (PMID 39183260, 2024).
small cell lung carcinoma (2 papers, 2023). Small cell lung cancer (SCLC) is a highly aggressive malignant neoplasm, accounting for 10-15% of lung cancer cases, characterized byrapid growth, and early metastasis. "The current results were consistent with the research conclusions in hematological tumors and small cell lung cancer, indicating that targeting UBA1 could increase the tumor cell sensitivity to IR, and the combined treatment of TAK-243 and IR may be a promising potential way to cure tumors." (PMID 36959858, 2023).
sweet syndrome (2 papers, 2025 to 2026). "Given the history of Sweet syndrome and concomitant inflammatory symptoms, genetic testing for UBA1 mutations was performed, revealing the UBA1 M41T." (PMID 39820409, 2025).
Turner syndrome (2 papers, 2022 to 2024). Turner syndrome is a chromosomal disorder associated with the complete or partial absence of an X chromosome. "Of the escape genes, SHOX, STS, KDM5C, KDM6A, UBA1, and RPS4X were associated with Turner syndrome." (PMID 36457060, 2022). "As UBA1 is located on the X chromosome, VEXAS affects predominantly men, but rare cases of women with acquired or constitutional (Turner syndrome) X monosomy have been reported." (PMID 39168911, 2024).
X-linked infantile spinal muscular atrophy (2 papers, 2011 to 2023). "More specifically, mutations in the UBA1-gene (or UBE1) have been associated with X-linked infantile spinal muscular atrophy, a neurodegenerative disease of the motor neurons." (PMID 21915392, 2011). "Up to December 2020, the UBA1 (Ubiquitin-Like Modifier-Activating Enzyme 1), encoding one of the two E1 enzyme isoforms that initiates ubiquitylation in cell’s cytoplasm, had been associated to the X-linked infantile spinal muscular atrophy in patients with germline mutations." (PMID 36662445, 2023).
acute GVHD (1 paper, 2025). "In contrast, the skin biopsy specimen from acute GVHD obtained 48 days after BMT suggested a reduced, but persistent presence of UBA1-mutant cells, with a VAF of 2.5%." (PMID 40846800, 2025).
alcoholism (1 paper, 2025). "The remaining cases without UBA1 variant showed evidence of copper deficiency, alcoholism, or MDS." (PMID 38819628, 2025).
ataxia telangiectasia (1 paper, 2018). Ataxia-telangiectasia is the association of severe combined immunodeficiency (affecting mainly the humoral immune response) with progressive cerebellar ataxia. "Poly(ADP-ribose) polymerase 1–dependent recruitment of UBA1 to DNA ensures ataxia-telangiectasia and RAD3-related activation." (PMID 30456359, 2018).
bladder cancer (1 paper, 2024). "The results show that the highest mutation frequency of UBA1 in bladder cancer patients is about 27%." (PMID 39183260, 2024).
brain tumours (1 paper, 2024). "The results showed that the expression of UBA1 was significantly increased in most cancers and the differential expression of UBA1 was mainly concentrated in digestive tumours, haematological tumours and brain tumours." (PMID 39183260, 2024). "UBA1 is significantly overexpressed in digestive tumours (COAD, ESCA, LIHC, PAAD, READ and STAD), haematological tumours (DLBCL and LAML/AML) and brain tumours (LGG and GBM)." (PMID 39183260, 2024). "Through analysing TCGA and GTEx data, we found that UBA1 is significantly overexpressed in gastrointestinal tumours (COAD, ESCA, LIHC, PAAD, READ and STAD), haematological tumours (DLBCL and LAML/AML) and brain tumours (LGG and GBM)." (PMID 39183260, 2024).
cervical squamous cell carcinoma (1 paper, 2024). A squamous cell carcinoma arising from the cervical epithelium. "UBA1 is significantly positively correlated with immune cell infiltration in cervical squamous cell carcinoma (CESC), cholangiocarcinoma (CHOL), ESCA, LUAD, MESO, OV and SKCM." (PMID 39183260, 2024).
chronic myeloid leukaemia (1 paper, 2018). "There are examples of cancer-derived cells, including acute and chronic myeloid leukaemia cell lines where UBA1 is closer to rate-limiting for ubiquitination." (PMID 29755650, 2018).
COVID-19 (1 paper, 2022). A disease caused by infection with severe acute respiratory syndrome coronavirus 2. "In particular, mutations in TNFRSF13B, UBA1, IRF2BP2, and FCN3 were already reported to be associated with severe COVID-19." (PMID 36552859, 2022).
depression (1 paper, 2024). "In particular, ribosomal protein S19, ribosomal protein S12, ribosomal protein S14, vimentin, and ubiquitin-like modifier activating enzyme 1 mediated the therapeutic effects of EXD on depression and hippocampal damage." (PMID 38915473, 2024).
dermatitis (1 paper, 2025). An inflammatory process affecting the skin. "Among the tested models, only depletion of Uba1 in NEs induced autoinflammatory symptoms including increased counts and percentages of NEs, increased proinflammatory cytokines, presence of vacuoles in myeloid cells, splenomegaly, and dermatitis." (PMID 40906528, 2025).
dermatomyositis (1 paper, 2025). Dermatomyositis (DM) is a type of idiopathic inflammatory myopathy characterized by evocative skin lesions and symmetrical proximal muscle weakness. "Inoue et al1 and Jia et al2 described the “angel wings” sign in Asian individuals with antismall ubiquitin-like modifier activating enzyme 1/2 (SAE1/2) antibody-positive dermatomyositis (DM)." (PMID 40353086, 2025).
dry eye (1 paper, 2019). "UBA1 has been associated with increased expression in the tear fluid of dry eye patients with both aqueous and lipid deficiency." (PMID 30976209, 2019).
endothelial dysfunction (1 paper, 2023). In vascular diseases, endothelial dysfunction is a systemic pathological state of the endothelium (the inner lining of blood vessels) and can be broadly defined as an imbalance between vasodilating and vasoconstricting substances produced by (or acting on) the endothelium. "This is in part likely due to decreased ubiquitylation as a result of UBA1 gene mutation, leading to chronic inflammation and haemostatic and endothelial dysfunction." (PMID 36617363, 2023).
fluorosis (1 paper, 2025). "In particular, we noted increased CFTR-linked proteins, such as LDHA, UBA1, implying that the latter may play a role in fluorosis." (PMID 41000239, 2025).
Infertility (1 paper, 2008). "In C. elegans, early events like meiosis appear unaffected by the uba-1(it129) mutation, suggesting that the infertility of these morphologically normal spermatozoa is due to a later defect in sperm development." (PMID 18636104, 2008). "Another possibility is that uba-1(it129) infertility might reflect a role for ubiquitin-mediated proteolysis in the sperm-oocyte interaction." (PMID 18636104, 2008).
kidney inflammation (1 paper, 2025). "While UBA1 mutations are known to occur in peripheral myeloid cells and are associated with neutrophilic dermatitis in VEXAS, their role in kidney inflammation remains uncertain." (PMID 40445522, 2025).
malaria (1 paper, 2020). Malaria is a serious and sometimes fatal disease caused by a parasite that commonly infects a certain type of mosquito which feeds on humans. "However, it has not been established that it targets UBA1 in the malaria parasite." (PMID 32569299, 2020).
monocytopenia (1 paper, 2025). "Although both neutrophils and monocytes harbor UBA1 mutations, in the marrow, there is a differentiation bias towards neutrophils over monocytes with increased expression in the CEBPA master transcription factor and decreased expression in IRF810; with notable monocytopenia in 30% of patients." (PMID 40394087, 2025).
muscular atrophy (1 paper, 2023). The loss of muscle tissue due to inactivity or disease. "Moreover, missense mutations that reduce UBA1 expression cause infantile spinal muscular atrophy X-linked 2 (SMAX2), a disease characterized by muscle weakness." (PMID 37963875, 2023).
Myelodysplasia (1 paper, 2023). Clonal hematopoietic stem cell disorders characterized by dysplasia (ineffective production) in one or more hematopoietic cell lineages, leading to anemia and cytopenia. "This is not unusual in patients with Behcet’s, but it raises the need to consider VEXAS and UBA1 genetic variants especially in males with myelodysplasia." (PMID 36617363, 2023).
pan (1 paper, 2024). "Therefore, the high degree of phosphorylation at the S46 site of UBA1 protein may be one of the reasons for poor prognosis in pan cancer." (PMID 39183260, 2024).
Pleuritis (1 paper, 2025). Inflammation of the pleura. "Elderly men with pleuritis, systemic inflammation, cytopenias, and bone‐marrow vacuolization may have VEXAS due to somatic UBA1 mutations." (PMID 41347012, 2025).
pneumonitis (1 paper, 2024). An inflammatory process affecting the lung parenchyma. "Genetic screening for UBA1 should be considered in patients with recurrent pneumonitis of unknown origin with elevated inflammatory markers and signs of cytopenia, especially if they require chronic steroids to control the disease." (PMID 38343641, 2024).
retinal degeneration (1 paper, 2020). Degeneration of the retina. "In published work, overexpression of Uba1 enhanced Tau-induced retinal degeneration, suggesting that the observed up-regulation likely promotes (amplifies) Tau toxicity." (PMID 32993812, 2020).
sarcoma (1 paper, 2024). A usually aggressive malignant neoplasm of the soft tissue or bone. "UBA1 was positively correlated with TMB in 9 types of tumours including STAD, UCEC, sarcoma (SARC), skin cutaneous melanoma (SKCM), PAAD, GBM, LUSC and LGG, while negatively correlated with TMB in THCA and KIRP." (PMID 39183260, 2024).
sterility (1 paper, 2008). "Sperm-specific sterility caused by the uba-1(it129) mutation was characterized in greater detail, beginning with the early events leading to spermatid formation." (PMID 18636104, 2008). "Since these uba-1(it129) animals are infertile due to sperm-specific sterility, we included as an additional control a strain containing spe-26(it112) (a temperature-sensitive, sperm-specific sterile mutation)." (PMID 18636104, 2008).
testicular germ cell tumours (1 paper, 2024). "The results from the TCGA database showed that there was a significant expression difference of UBA1 between stages in testicular germ cell tumours (TGCT), READ and uveal melanoma (UVM), the expression level of UBA1 gradually increased in UVM and DLBC." (PMID 39183260, 2024).
thromboses (1 paper, 2025). "While systematic screening for UBA1 mutations in men over 50 with unprovoked thromboses is not yet recommended, the diagnosis should be considered when systemic inflammation and hematological abnormalities are present." (PMID 39820409, 2025).
uterine carcinosarcoma (1 paper, 2024). A usually aggressive malignant neoplasm arising from the uterine corpus and less often the cervix. "Except for READ, SKCM, uterine carcinosarcoma (UCS) and UVM, the expression of UBA1 in most tumours is associated with the expression of the MMR gene." (PMID 39183260, 2024).
ZIKV infection (1 paper, 2025). "Overexpression and RNAi-mediated downregulation experiments suggest that UBA1 plays a proviral role during ZIKV infection, supporting the development of antiviral therapies aiming at disrupting this virus–host interaction." (PMID 39773572, 2025). "During ZIKV infection, UBA1 protein levels increase at least by twofold at 24 h post-infection." (PMID 39773572, 2025).